SIRT5 (sirtuin 5)
Diseases named in the same sentence as SIRT5 in open-access papers (continued):
Sharing a sentence is not in itself a finding about the gene and the disease.
cancer (continued). "The SIRT5 gene locus is commonly gained or lost in a variety of cancers, but typically in the context of non-focal genomic events that modify many neighboring genes in addition to SIRT5." (PMID 36980194, 2023). "Sirtuin 5 (SIRT5), an NAD+-dependent desuccinylase, is hypothesized to be a key regulator of various cancers." (PMID 35278714, 2023). "Moreover, RT-qPCR analysis revealed that SIRT5 and HDAC3 expression levels in cancer tissues were significantly higher than in normal tissues (p < 0.05)." (PMID 37705968, 2023). "Additionally, we identify a sirtuin family member, the NAD+-dependent de-succinylase Sirt5, as a key transcriptional target for ATF4 that promotes cancer cell survival during metabolic stress." (PMID 35963851, 2022). "SIRT5 also desuccinylates serine hydroxymethyl transferase (SHMT2), and the inactivation of SIRT5 downregulates SHM2 succinylation and decreases its activity in serine catabolism and inhibits cancer cell growth." (PMID 36010594, 2022). "A high level of SIRT5 desuccinylates SDH and reduces its activity promoting cancer cell proliferation, while SIRT5 silencing results in hyper-succinylation of SDHA and reactivates it, thus preventing the growth of cancer cells." (PMID 36010594, 2022). "Considering that cancer cells tend to adapt metabolic flux to restore nucleotide pool and avoid DNA damage, we subsequently examined metabolic changes in CRC cells with stable knockdown of SIRT5." (PMID 36253417, 2022). "SIRT5, SIRT6, and SIRT7 exhibited up-regulation in multiple cancer types." (PMID 32158696, 2020). "SIRT5 a binding partner of LDHB, promotes LDHB enzymatic activity by deacetylating LDHB at lysine-329 position leading to increased autophagy and accelerated growth of cancer cells." (PMID 31146503, 2019). "In summary, our findings revealed that SIRT5 is a regulator of cancer glutaminolysis via its activation of GLUD1 in a deglutarylation-dependent manner, suggesting SIRT5 as a promising anti-CRC target for the selective killing of cancer cells." (PMID 29416026, 2018). "Although FLT3 wild-type and mutant cancers present with comparable sensitivity to venetoclax, the levels and activity of SUCLG1, SIRT5, and POLRMT and the potential synergy between venetoclax and SIRT5 inhibitors should be further examined in FL3-IDT AML cases." (PMID 38724759, 2024). "Furthermore, overexpression of SIRT5 inhibits oxoglutarate dehydrogenase (OGDH), which in turn lowers ATP levels and raises ROS levels, thereby impairing the proliferation and migration of cancer cells." (PMID 36980194, 2023). "Additionally, we show that Sirt5 is a transcriptional target of ATF4 necessary for its pro-survival role in response to oxidative stress and conditions that negatively impact glutamine metabolism in cancer cells." (PMID 35963851, 2022). "Currently, the role of SIRT5 in cancer has not been widely reported." (PMID 32158696, 2020). "Thus, it was reasonable to believe that SIRT5‐deacetylated LDHB could promote the lysosomal acidification and, subsequently, autophagy, which are essential for cancer development." (PMID 30443978, 2019). "Furthermore, our in vivo growth assays showed that cancer cells overexpressing LDHBWT grew quicker than cells overexpressing LDHBK329Q, whereas the growth advantage induced by LDHBWT was blocked by the presence of SIRT5 inhibitor GW5074." (PMID 30443978, 2019). "However, the molecular mechanism of how suramin and resveratrol synergically regulate SIRT5 and, thus, play a joint role in cancer has not been clarified in detail, and this maybe a special case without generalization." (PMID 39979670, 2025). "However, compared to other SIRTs, the role of SIRT5 in cancer has not been extensively studied." (PMID 35278714, 2023). "The positive correlation of SUCLG1 expression with electron transport chain (ETC) components across numerous cancers suggests that SUCLG1 and SIRT5 influence POLRMT activity and mitochondrial biogenesis in non-AML cancers." (PMID 38724759, 2024).
infection (9 papers, 2018 to 2026). The state of being infected such as from the introduction of a foreign agent such as serum, vaccine, antigenic substance or organism. "For example, clusters 2 and 3 corresponded to genes with a lower expression in SIRT5-KO cells, independently of the infection status, and pathways linked to the cell cycle and cellular metabolism were significantly enriched in these clusters." (PMID 36095012, 2022). "Altogether, these data support the safety profile in terms of susceptibility to infections of SIRT5 inhibitors under development." (PMID 30515162, 2018). "To mimic clinical situations, we then explored the impact of SIRT5-deficiency on host defenses in models of infections induced by challenging mice with K. pneumoniae and S. pneumoniae i.n., E. coli i.p. and L. monocytogenes and S. aureus i.v." (PMID 30515162, 2018). "Quantitative real‐time polymerase chain reaction (qRT‐PCR) and western blot showed increased mRNA and protein levels of Sirt4 and Sirt5 in cardiomyocytes after Ad‐Sirt4 and Ad‐Sirt5 infection, respectively." (PMID 40842073, 2025). "The infection efficiency of AAV-SIRT5 and AAV-sh.SIRT5 in brain tissue was confirmed by western blot, showing that the protein level of SIRT5 was significantly increased in mice-treated AAV-SIRT5." (PMID 36517900, 2022). "To gain insight into the role of SIRT5 during SARS-CoV-2 infection, we performed RNA-seq in A549-ACE2 cells, WT and SIRT5-KO, after 3 days of infection with SARS-CoV-2 (MOI = 1)." (PMID 36095012, 2022). "They represent genes that are expressed at a higher basal level in SIRT5-KO cells, and whose expression is further increased during infection." (PMID 36095012, 2022). "We thus measured the recall response of memory Sirt5+/+ and Sirt5−/− OT-1 cells with the co-transfer model followed by secondary infection with relatively higher dose of bacteria." (PMID 34966740, 2021). "In the primary infection experiment, Sirt5+/+ and Sirt5−/− OT-1 cells have comparable expansion, early memory differentiation capacity, and effector function in the blood, spleens, and lymphocyte nodes, regardless of separate-transfer or co-transfer." (PMID 34966740, 2021). "Yet, upon secondary infection, we observed similar expansion, survival capacity, differentiation, and effector function between Sirt5+/+ and Sirt5−/− memory CD8+ T cells." (PMID 34966740, 2021). "Two days post-infection, the proportions of bacteremic mice (6/10 vs. 5/10) and blood S. pneumoniae loads (SIRT5+/+ vs. SIRT5−/−: 4.1 ± 2.2 × 103 CFU/ml vs. 4.8 ± 3.6 × 103 CFU/ml; mean ± SEM; P = 0.9) were equivalent in the two groups." (PMID 30515162, 2018). "During infection, SIRT5 protein abundance was significantly reduced." (PMID 41678546, 2026). "Here we investigated the role of SIRT5 during infection with SARS-CoV-2." (PMID 36095012, 2022). "The roles of SIRT5 in disease, infection, and aging, are unclear." (PMID 36095012, 2022). "SIRT5 is a critical metabolic enzyme that regulates several important metabolic processes, but its role during disease and infection is currently unknown." (PMID 36095012, 2022). "To determine if the proviral role of SIRT5 could be explained by its interaction with Nsp14, we analyzed the role of SIRT5 during infection with human coronavirus HCoV-OC43, a distantly related beta-coronavirus." (PMID 36095012, 2022). "Although Sirt5−/− OT-1 cells had slight survival advantage during contraction phase (14 days after infection) in the co-transfer model, consistent with separate transfer model, they formed the comparable ratio of early memory cell with Sirt5+/+ OT-1 cells in memory maintenance phase." (PMID 34966740, 2021). "Up to now, these data support the assumption that SIRT5 inhibitors should not increase patients' susceptibility to infections." (PMID 30515162, 2018). "Therefore, we sought to define the impact of SIRT5 in preclinical models of infections mimicking common clinical situations." (PMID 30515162, 2018).
infection (continued). "In the most stringent models, SIRT5 deficiency did not protect from lethal infection, as foreseen if SIRT5 would amplify cytokine response." (PMID 30515162, 2018). "To conclude, our results support the development of SIRT5 inhibitors for clinical purposes, as they suggest that these drugs would not increase patients' susceptibility to infections." (PMID 30515162, 2018). "Moreover, mitochondrial membrane potential detected by TMRE fluorescent dye was significantly decreased in Ad-RIP140 group, which could be recovered by the combined treatment of Ad-RIP140 infection and SIRT5 transfection." (PMID 39968093, 2025). "SIRT5 deficiency also did not render mice particularly susceptible to bacterial infections as suggested by the results obtained using models of sub-lethal/mild infection with K. pneumoniae, E. coli, L. monocytogenes, and S. aureus." (PMID 30515162, 2018). "Mass spectrometry and co-immunoprecipitation analyses indicated that infection upregulated the ubiquitin-conjugating enzyme ubiquitin C (UBC), enhanced its interaction with SIRT5, and promoted ubiquitin-mediated degradation of SIRT5." (PMID 41678546, 2026). "WT and SIRT5-KO cells were infected with SARS-CoV-2 (Wuhan strain, USA/WA-1/2020 isolate) at a multiplicity of infection (MOI) of 0.1 and 1, and viral RNA was quantified by RT-qPCR after 3 days." (PMID 36095012, 2022). "In the presence of sh-SIRT5, the apoptosis rate and the degeneration of hippocampal neurons in ICH rats were diminished by infection with sh-KLF6." (PMID 34149393, 2021). "To confirm these observations, we validated by RT-qPCR the upregulation of several restriction factors between WT and SIRT5-KO cells, in absence of infection." (PMID 36095012, 2022). "At the peak of expansion phase (seventh day after infection), we did not observe significant differences in the expansion of Sirt5+/+ and Sirt5−/− OT-1 cells." (PMID 34966740, 2021). "Therefore, SIRT5 may be not required for the function, differentiation, and survival of memory CD8+ T cells upon secondary infection." (PMID 34966740, 2021).
neurodegenerative disease (8 papers, 2008 to 2025). A disorder of the central nervous system characterized by gradual and progressive loss of neural tissue and neurologic function. "While SIRT3 to SIRT5 are known to be located in the mitochondrial matrix, only SIRT3 has been associated with neurodegenerative diseases through its regulation of calcium homeostasis." (PMID 40003583, 2025). "The expression of SIRT5 in the brain was reported to be decreased in neurodegenerative diseases such as Alzheimer’s disease." (PMID 36653443, 2023). "Given the reduced expression of SIRT5 in a number of degenerative diseases and the satisfying rescue effects from the restoration of SIRT5 in our work and others, targeting SIRT5 therapeutically is of interest." (PMID 36653443, 2023). "Mitochondrial SIRT5 has been considered as an important functional modulator of mitochondria, which contribute to ageing and neurodegenerative diseases." (PMID 27445698, 2016). "In addition to the role of SIRT3 in mitochondrial quality control in neurodegenerative diseases, recent studies have gradually started to investigate the roles of two other mitochondrial sirtuins, SIRT4 and SIRT5, in mitochondrial quality control." (PMID 31780922, 2019).
metabolic disease (7 papers, 2023 to 2025). A congenital disorder (due to inherited enzyme abnormality) or acquired (due to failure of a metabolically important organ) disorder resulting from an abnormal metabolic process. "Supplementing NAD+ precursors to restore SIRT5 desamoylation activity alleviates abnormal protein amoylation, thereby improving metabolic disorders and neurodegeneration—consistent with prior findings." (PMID 41476741, 2025). "Due to the important role of SIRT4 and SIRT5 in metabolic regulation, they have the potential to become a new direction in the treatment of metabolic diseases and tumors, and the development of related agonists or inhibitors will also become a hot field." (PMID 38773972, 2024). "The regulation of these metabolic pathways by SIRT5 underscores its potential as a therapeutic target for metabolic diseases and conditions involving altered mitochondrial function or metabolic imbalance." (PMID 38773972, 2024). "The specific knockout of SIRT5 in BAT leads to a sharp rise in protein succinylation and malonylation, which in turn affects the function of UCP1, triggering systemic energy metabolic disorders and impaired thermogenesis." (PMID 39408844, 2024). "NAD + metabolic disorders and mitochondrial dysfunction are also exhibited by neurodegenerative diseases such as PD, suggesting the NAD + –SIRT5–succinylation axis may also play a regulatory role." (PMID 41476741, 2025).
neurological diseases (4 papers, 2016 to 2022). "SIRT5 is an essential regulator of mitochondria that contributes to neurological diseases, and SIRT5 silencing remarkably worsened hippocampal neuronal loss and degeneration." (PMID 34149393, 2021). "The neuroprotection of SIRT5 in KA-induced epileptic seizure and neurodegeneration will improve our current knowledge of the nature of SIRT5 in central nervous system (CNS) and neurological diseases." (PMID 27445698, 2016). "However, till today, the effect and mechanism of SIRT5 in the regulation of mitochondrial biology, such as energy production, metabolism and intracellular signaling in healthy brain and neurological diseases are still poorly understood." (PMID 27445698, 2016). "Sirtuin 5 (SIRT5), localized in mitochondrial matrix, has been considered as an important functional modulator of mitochondria that contributes to ageing and neurological diseases." (PMID 27445698, 2016).
bacterial infections (3 papers, 2018 to 2022). "In particular, we demonstrated that the mRNA expression of SIRT5 was also decreased in purified antigen-specific memory CD8+ T cells after bacterial infection, indicating the potential roles of SIRT5 in regulating CD8+ T cell effector and memory differentiation." (PMID 34966740, 2021). "SIRT5-KO mice display no obvious phenotype and mount strong innate immune responses against several bacterial infections." (PMID 36095012, 2022). "Overall, SIRT5 does not worsen host defenses to bacterial infections under the conditions tested here." (PMID 30515162, 2018).
colorectal (3 papers, 2022). "SIRT5 overexpression is significantly correlated with poor prognosis in CRC, and scientists have found that glutamate dehydrogenase 1 (GLUD1) can be deglutarylated and activated via SIRT5 to promote cellular glutaminolysis, thus enhancing colorectal carcinogenesis." (PMID 35428309, 2022).
heart disease (3 papers, 2014 to 2025). "Evidence has revealed the potential roles of SIRT5 in various human heart diseases." (PMID 40243486, 2025). "As we delve deeper into the role of newly-found lysine modifications in heart disease, it may also be desirable to develop chemical screens for Sirt3 and Sirt5-specific modulators." (PMID 25228883, 2014).
kidney diseases (3 papers, 2019 to 2024). "Recent studies also highlight the involvement of SIRT5, another mitochondrial sirtuin that also localizes in peroxisomes, in the regulation of renal cell metabolism during kidney diseases." (PMID 39000044, 2024). "Collectively, these data suggest that SIRT5 may play a role in the course of renal disease by modulating peroxisomal FAO as an adjunct to mitochondrial lipid metabolism." (PMID 39000044, 2024).
central nervous system disorder (1 paper, 2025). A disease involving the central nervous system. "Nevertheless, further efforts are still necessary in the future to construct highly selective SIRT5 agonists with favorable pharmacokinetics and further to reveal its therapeutic benefit and mechanism in central nervous system disorders." (PMID 40865948, 2025).
hematological diseases (1 paper, 2022). "In an in silico approach, we conducted an analysis in the GEPIA database, and we validated the results of the present systematic review when we observed that the SIRT1, SIRT3, SIRT5 and SIRT6 genes are also up-regulated in onco-hematological diseases such as DBLC when compared with normal tissues." (PMID 36230534, 2022).
mitochondrial metabolic diseases (1 paper, 2025). "Therefore, the identification of SIRT5 small molecule agonists, including resveratrol derivatives BML-217 and MC3138, presents an effective therapeutic way to treat mitochondrial metabolic diseases and to relieve nerve injury." (PMID 40865948, 2025).
neurodevelopmental disorder (1 paper, 2024). A behavioral and cognitive disorder with onset during the developmental period that involves impaired or aberrant development of intellectual, motor, or social functions. "SIRT5 has an increased level of brain tissue expression levels but has not been priorly implicated in OCD or other neurodevelopmental disorders so far." (PMID 39722687, 2024).
SIRT5 also shares sentences with these, for which no sentence is quoted: cardiovascular diseases (5 papers); Insulin resistance (4); nonalcoholic fatty liver disease (4); breast tumor (2); cognitive deficits (2); endometriosis (2); lipid metabolic disorders (2); lymphoma (2); staphylococcal infection (2); acute lymphoblastic leukemia (1); acute promyelocytic leukemia (1); anemia (1); astrocytoma (1); benign prostatic hyperplasia (1); Bovine mastitis (1); brain cancer (1); cervical cancer (1); chronic kidney disease (1); colon adenocarcinoma (1); diabetic kidney disease (1); diabetic retinopathy (1); endometrial carcinoma (1); head and neck cancer (1); hepatitis B (1); Hypertension (1); hypertrophy (1); intracerebral hemorrhage (1); intracranial aneurysm (1); ischemic disease (1); left ventricular dilation (1).
A further 10 diseases each share a sentence with SIRT5 in 1 paper.